PIK3CA (phosphatidylinositol-4,5-bisphosphate 3-kinase catalytic subunit alpha)
Diseases named in the same sentence as PIK3CA in open-access papers (continued):
Sharing a sentence is not in itself a finding about the gene and the disease.
colorectal cancer (continued). "Additionally, the anti-tumor activity of CB839 in xenograft growth of PIK3CA-mutant CRC cells was enhanced by chemotherapeutic agent 5-fluorouracil without obvious dose-limiting toxicity, indicating the potential of the combination therapy for patients with PIK3CA-mutant colorectal cancer." (PMID 34200820, 2021). "By contrast, the mechanism underlying the regulatory effects of CDC42EP3 on colorectal cancer were demonstrated through the detection of cancer-related signaling including Akt, CDK6, Cyclin D1 and PIK3CA, a reflection of the downregulation of Akt, p-Akt, CDK6, Cyclin D1 and PIK3CA." (PMID 33726765, 2021). "Notably, PIK3CA mutations have been found to have a synergistic effect with mutational inactivation of PTEN in inducing drug resistance or in inducing poor prognosis with EGFR/KRAS comutations in nonsmall cell lung and colorectal cancer." (PMID 33827485, 2021). "Therefore, in the following experiments, we focused on whether aspirin has a better effect on PIK3CA mutant colorectal cancer by acting on PI3K/Akt/Raptor pathway." (PMID 32000660, 2020). "For PIK3CA, immunohistochemistry (IHC) detection in other solid lesions, the cut-off value describing positive samples was individually determined, e.g., in non-small cell lung cancer and colorectal cancer, the cut-off point was H-score ≥ 10; in stomach cancer it was for over 20% of stained cells." (PMID 33287350, 2020). "In addition, PIK3CA mutations are significantly associated with resistance to the anti-EGFR treatments panitumumab and cetuximab, as well as progression free survival in colorectal cancer patients." (PMID 31769426, 2019). "Additionally, our study identified cell models that may serve as ideal in vitro models to further clarify the molecular mechanisms of aspirin's anti-tumor effects in PIK3CA-mutant colorectal cancer." (PMID 29152088, 2017). "In line with this precision medicine approach, multiple observational studies of colorectal cancer patients have indicated that the beneficial effects of aspirin may be stronger for PIK3CA-mutant colorectal cancer than for PIK3CA-wild-type tumors, though other studies have shown alternate findings." (PMID 29152088, 2017). "Colorectal cancer patients with PIK3CA and KRAS mutations did not respond to therapy." (PMID 26404261, 2015). "However, regular use of aspirin after diagnosis is associated with longer survival among patients with mutated-PIK3CA colorectal cancer, but not among patients with wild-type PIK3CA cancer." (PMID 25388762, 2015). "The large effect of aspirin on colorectal cancers has been suggested to be unlikely due to effects on PIK3CA tumours alone as these only account for 10–20 % of such cancers, but there are many other potential aberrations in this pathway in cancers with which COX-2 inhibitors may interact." (PMID 23907184, 2013). "Furthermore, a phase I study of a recently developed mTOR inhibitor found that colorectal cancer patients with PIK3CA mutations had a higher response rate than those without mutations." (PMID 22994622, 2012). "To demonstrate the utility of our model to test potential therapies for colorectal cancer, we selected the PI3Kα-selective inhibitor, BYL719, to treat subcutaneously transplanted Pik3ca-mutant adenocarcinomas." (PMID 39093890, 2024). "For example, in the monitoring of advanced colorectal cancer, ctDNA enables the dynamic and repeated assessment of changes in multiple key molecules of the tumor, such as EGFR, ERBB2, PIK3CA, and MAP2K1, among others." (PMID 39184861, 2024). "The aim of the study is to assess expression levels of CPEB4, APC, TRIP13, EIF2S3, EIF4A1, IFNg, PIK3CA and CTNNB1 genes in tumors and peripheral bloods of colorectal cancer patients in stages I–IV." (PMID 33237662, 2021).
colorectal cancer (continued). "The present study attempts to explore the inhibitory impact of KA25 and KA39 derivatives on Akt1 and Akt2 phosphorylation in three colorectal cancer cell lines (HT-29, LoVo, and SW403) with specific PIK3CA and KRAS statuses." (PMID 33916378, 2021). "The mRNA levels of CPEB4, APC, TRIP13, EIF2S3, EIF4A1, IFNg, PIK3CA and CTNNB1 genes expressed in colorectal cancer tissue specimens, colorectal cancer blood samples, normal colon tissues and blood samples were analysed." (PMID 33237662, 2021). "Some biomarkers can be used to predict the survival benefit of aspirin in colorectal cancer, including PTGS2 (COX-2) expression and the effects of the PIK3CA gene." (PMID 32646396, 2020). "Detection of some genes such as c-MYC, KRAS, BRAF, PIK3CA, PTEN can be used as a predictor of colorectal cancer." (PMID 33014884, 2020). "Aspirin can regulate the proliferation, apoptosis, and autophagy of colorectal cancer (CRC) cells through the PI3K/Akt/Raptor pathway, affecting PIK3CA‐mutant CRC." (PMID 32394616, 2020). "Colorectal cancer (CRC) is a heterogeneous disease with a complex biology and a wide number of altered genes such as BRAF, KRAS and PIK3CA." (PMID 32066410, 2020). "Exogenous mutant PIK3CA expression was performed with HCT116, a colorectal cancer cell line, which showed increased 5-FU chemotherapy resistance." (PMID 29970892, 2018). "The three data points where the cancer incidence is greater than the linear regression expectation correspond to PIK3CA E545K, KRAS G12D, and KRAS G12V in colorectal cancer, a cancer whose incidence is considered to have an extrinsic exposure component." (PMID 28755461, 2017). "Equally prominent were genes PIK3CA (44%) in breast, KRAS (51%) in lung, and APC (70%) in colorectal cancers." (PMID 28371134, 2017). "Here, the authors present BaseScope, a mutation-specific RNA in situ hybridization assay and spatially map colorectal cancer and adenoma KRAS, BRAF and PIK3CA driver gene mutant subclones." (PMID 29222441, 2017). "However, one study indicates that regular use of aspirin after diagnosis only has beneficial effects among patients with mutated-PIK3CA (phosphatidylinositol-4, 5-bisphosphonate 3-kinase, catalytic subunit alpha) colorectal cancer, but not among patients with wild-type PIK3CA cancer." (PMID 26918349, 2016). "In addition, the frequency of PIK3CA mutation (15%) was comparable with that reported previously (15%); however, the NRAS mutation frequency (1.9%) was lower than previously reported data from 2,000 colorectal cancer patients in NSABP C-07 and C-08 trials (2.9%)." (PMID 26909603, 2016). "As with lung cancer, the most well-described driver alterations in colorectal cancer (for example, ‘hotspot alterations’ in KRAS, BRAF, NRAS and PIK3CA) are concordant between primary tumors and metastatic lesions." (PMID 25808843, 2015). "Mutant PIK3CA stimulates the PI3K/AKT pathway and promotes cell growth in various cancers, including colorectal cancer." (PMID 26090613, 2015). "Based on these observations, the KRAS/PIK3CA MT molecular subtype was identified as one of particular interest in the evaluation of alisertib and TAK-733, and a total of nine double-mutant colorectal cancer cell lines were selected for further assessment." (PMID 26136684, 2015). "In the LARC population studied here, the observed frequencies of tumor aberrations of KRAS, BRAF, PIK3CA, and ERBB2 were in the order of magnitude previously reported in colorectal cancer." (PMID 23226389, 2012). "In a preclinical study in colorectal cancer cells with or without KRAS and PIK3CA mutations, the combination of ribociclib with alpelisib was more effective than each drug alone in vitro and in vivo in mice xenografts." (PMID 40699853, 2025).
colorectal cancer (continued). "DLX6-AS1 was found to regulate PIK3CA and MTOR in colorectal cancer." (PMID 40149330, 2025). "The expression of SIGLEC9 was significantly elevated in colorectal cancer tissues, independent of mutations in the KRAS, NRAS, BRAF, PIK3CA, and AKT genes, as well as MSI status." (PMID 39727942, 2024). "For example, colorectal cancer (CRC) patients with coexisting KRAS and PIK3CA (phosphatidylinositol 4,5-bisphosphate 3-kinase catalytic subunit alpha) mutations, do not respond to therapy." (PMID 39056802, 2024). "Finally, the six selected genes (SIRT3, PIK3CA, ITGA3, DAPK1, PAK1, and CASP3) have been reported in colorectal cancer." (PMID 38213716, 2024). "Survival of colorectal cancer patients of the TCGA was not different in the groups with BRAF and PIK3CA mutated or both genes mutated compared with cancers with both genes being wild type (Log Rank p = 0.9)." (PMID 36079062, 2022). "Intriguingly, cumulative evidence has demonstrated a significant survival advantage in patients with PIK3CA-mutant, but not wild-type, colorectal cancer who began regular NSAID use (aspirin) following diagnosis." (PMID 35158773, 2022). "Mutations in PIK3CA are not mutually exclusive with BRAF mutations and occur in both BRAF mutated and wild type colorectal cancers." (PMID 36079062, 2022). "The most frequent amplified locus in colorectal cancer at chromosome 20q11.21 is observed exclusively in cancers with wild type BRAF, with or without mutations in PIK3CA (in about 10% of cases in TCGA, not shown)." (PMID 36079062, 2022). "Moreover, therapeutic experiences clearly indicated that hEx3, unlike conventional anti-EGFR antibodies, was effective against colorectal cancer (CRC) cells with mutant KRAS, BRAF, or PIK3CA." (PMID 32666260, 2021). "For instance, miR-422a was confirmed to inhibit glioma cell proliferation, invasion, and migration by targeting PIK3CA, which is a critical member of PI3K/Akt signal pathway; miR-422a was proven to directly target AKT1 to inhibit PI3K/Akt pathway and colorectal cancer cell proliferation." (PMID 34715879, 2021). "Neither colon syngeneic model has an APC mutation, which is mutated in the majority of human colorectal cancer and neither the breast-derived tumor model EMT6 nor 4T1 have activating mutations in PIK3CA." (PMID 31898484, 2020). "We found that there was inconsistency in the frequency distribution of CNAs in both of the data sets for those actionable genes from our list which are considered promising druggable targets for NSCLC, and colorectal cancer, such as KRAS, BRAF, EGFR, ATM, and PIK3CA." (PMID 30728399, 2019). "Although we conducted four human colorectal cancer cell lines in this experiments, did not confirm other human colorectal cancer cell lines harboring KRAS, BRAF and PIK3CA mutation and patients-derived MEK inhibitor resistance colorectal cancer cells." (PMID 31769426, 2019). "A greater understanding of colorectal cancer biology followed by use of EGFR-targeted treatments has led to discovery of the importance of BRAF, PIK3CA, KRAS, and NRAS mutations in predicting a lack of response to EGFR-targeted therapy." (PMID 29254887, 2018).
colorectal cancer (continued). "Although both cell lines originate from human colorectal cancers, they have a very different mutational profile, with HCT116 cells harboring a H1047R mutation in PIK3CA gene, whereas CACO-2 cells do not." (PMID 27716613, 2016). "In contrast, 8 patients (colorectal cancer, n = 4; squamous cell head and neck, n = 1; non-squamous head and neck cancer, n = 1; breast, n = 1; NSCLC, n = 1) had PIK3CA E542K or E545K mutations in cfDNA but not in FFPE tumor samples." (PMID 25980577, 2015). "The most striking and consistent finding that we and others have found is the association between PIK3CA mutation and KRAS mutation in colorectal carcinoma, though some have not reported this finding." (PMID 23785428, 2013). "A paired analysis of colorectal cancer patients for whom we had data on the last FDA-approved therapy and phase I therapy (PIK3CA mutations, n=10; wt PIK3CA, n=25), there was no response noted." (PMID 23248156, 2012). "Colorectal cancers lacking oncogenic alterations in genes encoding EGFR downstream effectors such as KRAS, BRAF, PIK3CA, and PTEN have the highest probability of response to anti-EGFR therapies." (PMID 22152101, 2011). "Recently a number of randomized trials have shown that patients with advanced colorectal cancer do not benefit from therapies targeting the epidermal growth factor receptor when their tumors harbor mutations in the KRAS, BRAF and PIK3CA genes." (PMID 20098682, 2010). "This study found noevidence of PIK3CA gene amplification in 96 colorectal cancers, suggesting that amplification is not a common mechanism of activation in this tumor type." (PMID 19384426, 2007). "Researchers have discovered many genes related to the occurrence and development of colorectal cancer through genomic studies, including but not limited to the PIK3CA, KRAS, APC, SMAD4, and BRAF genes, among which the PIK3CA gene has attracted widespread attention." (PMID 39555098, 2024). "Unveiling vulnerabilities of colorectal cancers with BRAF mutations with and without concomitant PIK3CA mutations may provide new opportunities for targeted treatments." (PMID 36295658, 2022). "Importantly, PIK3CA inhibitors currently show promise in the treatment of some hematologic and breast neoplasias, but not in colorectal cancer." (PMID 32019056, 2020). "In addition, patients with colorectal cancer harboring KRAS, BRAF or PIK3CA mutations have poor prognosis compared to patients without these mutations." (PMID 31769426, 2019). "RAPTOR dysregulation was also implicated in a study of colorectal cancer: compared with cells that were either mutant or wild-type for both KRAS and PIK3CA, non-isogenic KRAS-mutant cells were reported to be relatively resistant to mTOR kinase inhibitor PP242, and to modestly overexpress RAPTOR." (PMID 29389967, 2018). "Evidence suggests that nonsteroidal anti-inflammatory drug aspirin (acetylsalicylic acid) may improve patient survival in PIK3CA-mutant colorectal carcinoma, but not in PIK3CA-wild-type carcinoma." (PMID 29152088, 2017). "Taken together, these data indicate that miRs-134 and -370 are potential tumour suppressor miRNAs and could play a fundamental role in suppressing colorectal cancer tumorigenesis through their ability to co-ordinately regulate EGFR signalling cascade by independently targeting EGFR and PIK3CA." (PMID 27095166, 2016). "Multivariate analysis showed that NDRG4 could be a prognostic factor for overall survival of patients with colorectal cancer independent of gender, age, differentiation status, TNM stage, KRAS, BRAF and PIK3CA mutations and MSI status." (PMID 26515606, 2016). "Multivariate analysis showed that NEAT1 expression could be a prognostic factor for overall survival of patients with colorectal cancer independent of gender, age, differentiation status, TNM stage, MSI, KRAS, BRAF and PIK3CA mutation." (PMID 26314847, 2015).
colorectal cancer (continued). "Recently a number of randomized trials have shown that treatment of patients with advanced colorectal cancer (CRC) do not benefit from therapies targeting the epidermal growth factor receptor (EGFR) when their tumors harbor mutations in the KRAS, BRAF and PIK3CA genes." (PMID 20098682, 2010). "This could be due to the absence of PIK3CA mutation in half of colorectal cancer patients, and the frequent co-occurrence of KRAS pathogenic variants with PIK3CA mutations, leading to a shorter reported PFS and potentially reduced activity against PIK3CA inhibitors." (PMID 39070139, 2024). "According to the subgroup analysis in our study, the effects of aspirin use on PIK3CA gene mutation and survival of patients with high expression of PTGS2 (COX-2) was different from that of patients with wildtype PIK3CA and PTGS2 (COX-2)-negative colorectal cancer." (PMID 32646396, 2020).